TOP2A (DNA topoisomerase II alpha)
Diseases named in the same sentence as TOP2A in open-access papers (continued):
Sharing a sentence is not in itself a finding about the gene and the disease.
breast carcinoma (continued). "Moreover, UBE2C inhibition sensitized breast cancer cells to doxorubicin by downregulating the expression of TOP2A." (PMID 40729680, 2025). "The mRNA expression of UBE2C positively correlated with that of TOP2A in breast cancer." (PMID 40729680, 2025). "Bioinformatics analysis was performed to verify the expression level of TOP2A in breast cancer." (PMID 40729680, 2025). "Moreover, UBE2C inhibition also sensitized breast cancer cells to doxorubicin by downregulating TOP2A and aggravating doxorubicin‐induced cellular senescence." (PMID 40729680, 2025). "TOP2A was significantly overexpressed in breast cancer cells at both the mRNA and protein levels." (PMID 40729680, 2025). "Moreover, the inhibition of UBE2C downregulated the expression of TOP2A to sensitize breast cancer cells to doxorubicin and aggravate doxorubicin‐induced senescence." (PMID 40729680, 2025). "Third, the biological complexity of fascin and TOP2A suggests that their role in breast cancer may depend on indirect mechanisms or interactions with other molecular pathways not fully captured by IHC or FISH." (PMID 40243780, 2025). "TOP2A was shown to be prognostic in estrogen receptor-positive breast carcinomas." (PMID 39195643, 2024). "Our findings also showed that breast cancer patients with TOP2A, ERBB2, and MYC amplification (amp) achieved higher pCR rates than wtTOP2A, ERBB2, and MYC (56.3% (n=1) vs 13.8% (n=1), 28.4% (n=1) vs 6.1% (n=1), and 13.7% (n=1) vs 11.2% (n=1), respectively) when treated with TA regimens." (PMID 38576013, 2024). "Moreover, we found six sex-biased genes (EGFR, CDK6, PRKCB, PDCD1, KCNH2, FCGR3B, and TOP2A) in BRCA were the therapeutic targets of breast cancer." (PMID 39175079, 2024). "Furthermore, scatter plot of cyclin D1 and Top2A abundance by breast cancer subtype depicts the significant correlation between cyclin D1 and Top2A in luminal B (r = 0.08." (PMID 38191593, 2024). "For gene TOP2A, it has been proposed that the HER2 amplification in HER2 breast cancers may be a direct result of the frequent co-amplification of TOP2A, and there is a high correlation between the high expressions of TOP2A and the oncogene HER2." (PMID 38741183, 2024). "Furthermore, Topoisomerase IIα (TOP2A) is O-GlcNAcylated, which promotes malignant tumor progression in breast cancer and resistance to adriamycin by stimulating the binding of TOP2A to chromatin and its topoisomerase activity." (PMID 39491647, 2024). "TOP2A is overexpressed in various human malignancies, including primary breast cancer, lung cancer, hepatocellular carcinoma, nasopharyngeal carcinoma, adrenal cortex, and colon cancer, indicating that TOP2A is an important drug target and a potential biomarker for these cancers." (PMID 37048139, 2023). "Topoisomerase alpha 2 (TOP2A), a gene located in 17 q12–21 and consisting of two subunits, is a marker of proliferation and chemotherapy resistance in various cancer types, including adrenocortical carcinoma and breast carcinoma." (PMID 37244966, 2023). "TOP2A could act as a predictor of response to epirubicin in the neoadjuvant treatment of breast cancer." (PMID 35211510, 2022). "In this study, we used the CPTAC dataset to explore the molecular mechanisms of TOP2A protein in breast cancer, clear cell renal cell carcinoma, lung adenocarcinoma, ovarian cancer, and uterine corpus endometrial carcinoma in terms of total protein and phosphoprotein levels." (PMID 35873470, 2022). "Aberrant expression of TOP2A has been identified in many tumors, including lung adenocarcinoma, hepatocellular carcinoma, adrenocortical carcinoma, neuroblastic tumors, prostate cancer, and breast cancer." (PMID 35211510, 2022). "Highly expressed TOP2A has been reported to promote breast cancer progression." (PMID 35945960, 2022).
breast carcinoma (continued). "In addition, the high expression of TOP2A can be shown in various relevant research reports to be closely related to poor prognosis of lung cancer, bladder urothelial carcinoma, breast cancer, adrenal cortical carcinoma and other cancers." (PMID 35033076, 2022). "A prognostic SLEscore consisting of five SLE-related genes (RACGAP1, HMMR, TTK, TOP2A, and KIF15) could distribute patients with breast cancer into the high- and low-risk groups according to survival rates with good predictive ability (p < 0.05)." (PMID 36726984, 2022). "During the docking analysis, it was noted that out of the 44 compounds, Ashwagandhanolide and Withanolide sulfoxide had the potentiality to inhibit the four different proteins (viz., ERα, 17β-HSD1, TOP2A and p73 tetramerization domain) responsible for breast cancer." (PMID 36201520, 2022). "Previous studies have suggested that TOP2A was upregulated and indicative of poor prognosis in many malignancies including lung adenocarcinoma, gastric cancer, breast cancer, and prostate cancer, which is noteworthy." (PMID 35784467, 2022). "TOP2A is involved in many cancers, being a prognostic biomarker and potential therapeutic target for bladder cancer, lung adenocarcinoma, prostate cancer, colon cancer, breast cancer, and HCC." (PMID 36557005, 2022). "Furthermore, TOP2A was identified as a therapeutic target for breast cancer, small-cell lung cancer, ovarian cancer, and leukemia." (PMID 35251970, 2022). "In addition, CENPE and TOP2A are upregulated in a number of solid cancers and are involved in mitotic cell cycle nodes in breast cancer." (PMID 35496042, 2022). "In addition, patients with TOP2A high expression showed a significantly higher rate of distant metastasis in early stage luminal breast cancer." (PMID 36288358, 2022). "Additionally, TOP2A, as a prognostic factor and oncogene, is associated with LUAD survival, breast cancer, and prostate cancer." (PMID 35251970, 2022). "HER2 and TOP2A are usually coamplified in HER2-amplified breast cancer." (PMID 34737790, 2021). "In addition, SETMAR interaction with TOP2A has been found to enhance TOP2A function in chromosome decatenation and to promote resistance to topoisomerase II inhibitors in breast cancer cells." (PMID 34947873, 2021). "The selective activity of anthracyclines in HER2-amplified breast cancer could be related to the simultaneous amplification of the Top2a gene, the main target of anthracyclines, placed in the same amplicon as the HER2/neu gene." (PMID 33782404, 2021). "Accumulating researches have shown that TOP2A is overexpressed in many types of tumors, such as pancreatic cancer, breast cancer, prostate cancer, colon cancer, gastroesophageal and esophageal cancer, hepatoblastoma and malignant peripheral nerve sheath tumor 9-12." (PMID 32201520, 2020). "TOP2A could induce tumor development and progression in many cancer types, including PC, prostate cancer and breast cancer." (PMID 32850392, 2020). "Studies have found that high expression of TOP2A promoted the progression of breast cancer." (PMID 31422942, 2019). "In this work, the ERBB2 and TOP2α DNA and RNA status were analyzed and compared between 27 fresh feline mammary tumor (FMTs) samples and disease-free tissues (DFT) collected from the same animals, being these profiles integrated with clinicopathological features." (PMID 31301170, 2019). "The current study for the first time demonstrated the worse and time dependent prognostic impact of TOP2A overexpression in early stage luminal breast cancer patients, suggesting the potential value of TOP2A as a predictor of late recurrence for this subtype of breast cancer." (PMID 29587760, 2018). "The current study evaluated the prognostic impact of TOP2A protein on luminal breast cancer." (PMID 29587760, 2018).
breast carcinoma (continued). "In our study, we also used IHC analysis to evaluate TOP2A overexpression as a significant prognostic factor in luminal breast cancer; however, the prognostic value was restricted in luminal B breast cancer, defined as tumors with high Ki67 index and/or low PgR expression." (PMID 29928479, 2018). "Another probable reason may be due to different prognostic impact of TOP2A protein on different subtypes of breast cancer." (PMID 29587760, 2018). "TOP2A protein showed a time dependent influence on prognosis in stage I-II luminal breast cancer, suggesting it might be a potential predictor of late recurrence for this group of patients." (PMID 29587760, 2018). "Thus, the characteristics of TOP2A amplified breast cancer reflected those of HER2 positive breast cancer." (PMID 29928479, 2018). "TOP2A amplified was recognized in HER2 positive breast cancer (p < 0.001)." (PMID 29928479, 2018). "The prognostic effect of TOP2A seems different among different subtypes of breast cancer." (PMID 29587760, 2018). "Considering the excellent prognosis of HER2-positive breast cancer, to facilitate the decision of adjuvant anthracycline therapy based on the evaluation of TOP2A amplified may lack clinical meaning." (PMID 29928479, 2018). "The prognostic effect of TOP2A protein expression on breast cancers is still in debates." (PMID 29587760, 2018). "There was sparse evidence from level III retrospective studies and level IV pre-clinical studies supporting the chemosensitizing effect of TOP1 and TOP2A overexpression in response to camptothecin-based therapies and anthracyclines in gastrointestinal and breast cancers respectively." (PMID 27888622, 2017). "Top2a codes for topoisomerase II Alpha, a key enzyme in DNA replication that regulates gene expression and cell division and whose amplification is a predictor for anthracycline treatment in breast cancer." (PMID 28212608, 2017). "Genes enriched in the top breast cancer cell lines are TOP2A, HER3, CDC25B, MCM2 and TUBB." (PMID 28754978, 2017). "This indicates that TOP2A may be a marker gene relevant to docetaxel resistance in breast cancer patients." (PMID 26824188, 2016). "In fact, PCNA, TOP2A and other genes in the patterns have been targets for breast cancer therapy." (PMID 27004791, 2016). "The HER2/TOP2A locus is of great importance in breast cancer." (PMID 26022247, 2015). "TOP2A expression is strongly correlated with Ki-67 expression in breast cancer." (PMID 25695068, 2015). "TOP2A gene pathology (amplification, deletion and combinations of both) has been reported as a favorable prognostic and predictive marker in adjuvant-treated breast cancer patients." (PMID 23537287, 2013). "According to this work, protein expression might be more relevant than TOP2A amplification or deletion in predicting the outcome of breast cancer patients that received anthracycline-based chemotherapy." (PMID 23398928, 2013). "Formalin-fixed paraffin-embedded tumor tissue samples from 1031 patients with high-risk operable breast cancer, enrolled in two consecutive phase III trials, were assessed in a central laboratory by fluorescence in situ hybridization for HER2/TOP2A gene amplification and CEP17 gain (CEP17 probe)." (PMID 23537287, 2013). "Since TOP2A amplified tumor cells tend to be sensitive to topo-II inhibitor therapy while TOP2A deleted tumor cells tend to be resistant to anthracycline chemotherapy, the overall response of a given breast cancer case will depend on the relative proportions of the 2 cell types." (PMID 21785684, 2011). "Since our analysis showed that RAD21 expression strongly correlates with TOP2A expression in a number of breast cancer cell lines, we assessed the sensitivity of RAD21 knockdown clones to etoposide, a topoisomerase II inhibitor and commonly used anti-cancer drug." (PMID 21255398, 2011).
breast carcinoma (continued). "Recent evidence suggests that amplification or deletion of TOP2A gene may account for sensitivity or resistance to topo II-inhibitor (anthracycline) therapy in breast cancer." (PMID 21785684, 2011). "In addition, several breast cancers have shown TOP2A amplification and overexpression; which makes them particularly susceptible to Top2 poisons." (PMID 20824055, 2010). "TOP2A alterations may contribute to pathogenesis in HER2+ breast carcinomas by altering sensitivity to anthracyclines." (PMID 18854030, 2008). "Previously published reports suggest that TOP2A amplification and deletion account for relative chemosensitivity and chemoresistance, respectively, to TOP2A inhibitor therapy depending on the specific genetic defect at the TOP2A locus in breast carcinoma." (PMID 19061514, 2008). "Many reports have shown that HER2 and TOP2A co-amplification predicted a good response to TOP2A inhibitor chemotherapy in breast carcinoma, and that a combined therapy with HER2 inhibitors and TOP2A inhibitors would be a good choice for the treatment of these cancer patients." (PMID 19061514, 2008). "In breast cancer, gene copy aberrations of the TOP2A gene have been detected." (PMID 16280042, 2005). "Moreover, the TOP2α gene being located at 17q12–21 close to the Her-2/neu oncogene, coamplification of the Her-2/neu and TOP2α genes was observed in 44% of breast cancers, whereas the TOP2α was deleted in another 42%." (PMID 12915875, 2003). "Moreover, UBE2C knockdown reduced the protein stability of TOP2A in breast cancer cells." (PMID 40729680, 2025). "Thus, we hypothesized that UBE2C knockdown sensitized breast cancer cells to doxorubicin through the synergistic inhibition of TOP2A." (PMID 40729680, 2025). "Moreover, UBE2C knockdown promoted the ubiquitination of TOP2A in breast cancer cells." (PMID 40729680, 2025). "Furthermore, TOP2A was a recently identified target of anti-cancer drugs, such as Anthracyclines (approved for the treatment of breast cancer) and Etoposide (approved for treating small-cell lung cancer, ovarian and testicular, choriocarcinoma, lymphoma, and acute myeloid leukemia) 4, 21-25." (PMID 32201520, 2020). "TOP2A overexpression was significantly associated with relapse-free survival in luminal B breast cancer (n = 316; log rank test, p < 0.001) but not in other breast cancer subtypes." (PMID 29928479, 2018). "In contrast, TOP2A amplified could be a better prognostic factor in HER2 positive breast cancer." (PMID 29928479, 2018). "Additionally, TOP2A is a molecular target of anthracycline, and previous reports have shown that TOP2A amplified or deleted are predictive markers of anthracycline-containing adjuvant chemotherapy regimens for early breast cancer." (PMID 29928479, 2018). "For example, two meta-analyses recently concluded that breast cancer patients with amplification of the topoisomerase 2A (TOP2A) gene have more clinical benefit from treatment with topoisomerase II inhibitors than patients with normal TOP2A gene number in their cancer cells." (PMID 24400218, 2013). "In breast cancer specimens and cell lines, it was discovered that MALAT-1 and TOP2A expressions were dramatically elevated, whereas miR-561-3p expressions decreased." (PMID 38511067, 2024). "We next determined the expression of RRM2, CDC6, and TOP2A mRNA and protein in XBP1-knockout sub-clones of MCF7 cells and ER-positive (MCF7, T47D, and BT474) breast cancer cells after treatment with STF083010." (PMID 36997866, 2023). "The novel prognostic SLEscore with five key therapeutic targets (RACGAP1, HMMR, TTK, TOP2A, and KIF15) was developed for the management of breast cancer patients with SLE using the LASSO algorithm." (PMID 36726984, 2022).
breast carcinoma (continued). "CDC20, TOP2A, RRM2, and UBE2C were highly expressed not only in HCC, but also in breast cancer and other tumors." (PMID 34568357, 2021). "Four hub genes, namely TOP2A (p=0.036), MELK (p=0.021), PBK (p=0.043), and RRM2 (p=0.012), were upregulated during breast cancer progression from normal tissue to DCIS and downregulated during disease progression from DCIS to IDC." (PMID 34094915, 2021). "For example, two early studies evaluating HER2 and TOP2A alterations by FISH in breast tumors (N = 136128 and N = 97125) indicated that over 40% of HER2 amplified breast cancers have TOP2A co-amplification." (PMID 34625570, 2021). "In breast cancer (BC) HER‐2 and TOP2A are the molecular targets for several anticancer medicines that are bolstered together." (PMID 34249670, 2021). "The breast cancer subnetwork is found to contain (i) valid biomarkers including PIK3CA, PTEN, BRCA1, AR and EGFR; (ii) validated drug targets TOP2A, CDK4, HDAC1, IL6, BRCA1, HSP90AA1 and AR; (iii) synergistic drug targets EGFR and BIRC5." (PMID 35053185, 2021). "TOP2A was reported to be frequently co-amplified with HER-2 and then reduce the clinical outcome in urinary bladder cancer and breast cancer." (PMID 31043166, 2019). "Additionally, TOP2A might be an important therapeutic target in etoposide resistant breast cancer." (PMID 31139019, 2019). "Although feline mammary tumors (FMTs) are good models in comparative oncology, scarce data is available regarding the ERBB2 and TOP2α status." (PMID 31301170, 2019). "In this study we evaluate the potential MGMT’s role in control of therapeutic, clinically relevant, cell cycle regulators involved in breast cancer oncogenesis (CDC2, TOP2A, AURKB, CDC20, KIF20A, Cyclin A2, Cyclin B2, Cyclin D1)." (PMID 30038716, 2018). "We show that O6-benzylguanine (BG), an MGMT inhibitor decreases CDC2, CDC20, TOP2A, AURKB, KIF20A, cyclin B2, A2, D1, ERα and survivin and induces c-PARP and p21 and sensitizes ER positive breast cancer to temozolomide (TMZ)." (PMID 30038716, 2018). "In many tumors, such as breast cancer, head, and neck squamous cell carcinoma and NSCLC, TOP2A expression is significantly higher in middle and low differentiated tumors than in high differentiated ones." (PMID 30369945, 2018). "Among them, 5 (TOP2A, HER3, CDC25B, MCM2 and TUBB) are from breast cancer cell lines and, in particular, HER2 positive cells (ZR7530 is [ER+PR−]HER2+, HCC2218 and BT474 are [ER−PR−]HER2+78)." (PMID 28754978, 2017). "TOP2A and TYMS were found significant up-regulated genes in Triple Negative breast cancer cells, as compared to normal cells." (PMID 26892392, 2016). "As TOP2A, TYMS is also a gene from the Triple Negative pattern which is a target gene of three Breast cancer drugs (Fluorouracil, Gemcitabine and Capecitabine)." (PMID 26892392, 2016). "Soares and colleagues analyzed the status of the topoisomerase II alpha gene (TOP2A) in the FMCs referred above, as the status of these two genes, ERBB2 and TOP2A, is usually “in accordance” in some human breast cancers." (PMID 29056725, 2016). "A variety of genes, including PIK3CA, PTEN, TOP2A and MET are candidate markers for prognosis and response to treatment in ERBB2-positive breast cancer." (PMID 27576528, 2016). "These chromosomes contain genes that are commonly involved in the invasion, metastasis and pathogenesis of breast cancer, including c-MYC on 8q24; HRAS, CD151, CTSD on 11p15; CCND1 on 11q13; and TOP2A on 17q21." (PMID 24456987, 2014). "The computational pipeline was applied to a panel of 45 breast cancer cell lines, and the protocol identified a list of 58 genes, including COL1A2, TOP2A, TFF1, and VAV3, whose key roles in epigenetic regulation are consistent with known literature." (PMID 20525369, 2010).